ASGR1 (asialoglycoprotein receptor 1)
Diseases named in the same sentence as ASGR1 in open-access papers (continued):
Sharing a sentence is not in itself a finding about the gene and the disease.
tumor (56 papers, 2010 to 2025). "In addition, the combined loss of ASGR1 and miR-122-5p in CECs indicates a dedifferentiation tendency of tumor cells and is closely associated with poorer progression-free survival (PFS)." (PMID 40852369, 2025). "Thus, T cells carrying two complementary CARs against GPC3 and ASGR1 may reduce the risk of off-tumor toxicity while maintaining relatively potent antitumor activity on GPC3+ASGR1+ HCC." (PMID 34071188, 2021). "Research indicates that ASGR1 exerts tumor-suppressive effects by inhibiting phosphorylation of the STAT3 signaling pathway." (PMID 40852369, 2025). "ASGR1 expression is also closely associated with immune cell infiltration, including B cells, CD8+ T cells, and DCs, indicating its role in tumor microenvironment immune modulation." (PMID 40852369, 2025). "Dual-targeted CAR-T cells co-expressing GPC3 and asialoglycoprotein receptor 1 (ASGR1) exhibited cytotoxicity against GPC3+ASGR1− and GPC3+ASGR1+ HCC cells in vitro and caused a significant reduction of GPC3+ASGR1+ HCC tumor xenografts in vivo." (PMID 37420216, 2023). "When tumors arose (7–9 months of age), both tumors and adjacent non-tumor tissues were collected and ASGR1/2 mRNA levels were measured by qRT-PCR." (PMID 31303442, 2019). "While ASGR1/2 mRNA levels in adjacent non-tumor tissues were comparable to those of liver from age-matched normal mice, the receptor expression was reduced by ∼50%–60% in liver tumors." (PMID 31303442, 2019). "Moreover, ASGR1 was highly expressed in HUH7‐formed orthotopic tumor xenografts and had similar levels in the normal liver tissues of mice." (PMID 35603967, 2022). "Therefore, our result is consistent with the previous report and suggests the role of ASGR1 as a tumor suppressor in HCC." (PMID 35327967, 2022). "In another experiment, T cells with two complementary CARs against GPC3 and asialoglycoprotein receptor 1 (ASGR1) decreased the risk of on-target, off-tumor toxicities and demonstrated potent antitumor immune responses targeting GPC3+ ASGR1+ HCCs both in vivo and in vitro." (PMID 29785403, 2018). "Furthermore, variable ASGR1 expression was observed between tumor stages." (PMID 36518850, 2022). "One notable example is the glycosylated prodrug Gal-DOX, which incorporates a galactose moiety to facilitate selective binding to the asialoglycoprotein receptor 1 (ASGPR1), commonly overexpressed on specific tumor cells." (PMID 40868286, 2025). "Multiple studies have reported significant downregulation of ASGR1 expression in HCC tissues, with expression levels decreasing further as tumor progression and grading advance." (PMID 40852369, 2025). "Metastatic tumors in mouse lungs also expressed high levels of ASGR1, which suggested that HUH7‐formed orthotopic tumor xenografts are an ideal model for evaluating the therapeutic effect of GalNac‐siHK2." (PMID 35603967, 2022). "Further analysis revealed that ASGR1 expression in CECs remains detectable in the early stages of HCC, such as in LC patients with lower Child-Pugh scores, suggesting its potential as a non-invasive tool for early tumor monitoring." (PMID 40852369, 2025). "Specifically, ASGR1 interacts with Nemo-like kinase (NLK) to inhibit glycoprotein 130/janus kinase 1 (GP130/JAK1)-mediated STAT3 phosphorylation, thereby blocking the activation of STAT3-related pro-tumor signaling pathways." (PMID 40852369, 2025). "Beyond acting as a tumor suppressor during HCC development, ASGR1 expression on circulating cells may serve as an effective liquid biopsy marker for early screening, risk stratification, and treatment monitoring." (PMID 40852369, 2025). "Interestingly, with the exception of ASGR1, which is expressed in HCC tumor cells and known to prevent metastasis, SCARF1 was the only other scavenger receptor gene which was associated with increased survival in HCC." (PMID 34354939, 2020).
tumor (continued). "Dual-targeting CAR-T cells coexpressing GPC3 and asialoglycoprotein receptor 1 (ASGR1, a liver tissue-specific protein) targeting CAR’s featuring CD3 zeta chain (CD3ζ) and 28BB (containing both CD28 and 4-1BB signaling domains) have been tested in a GPC3+ASGR1+ HCC tumor xenograft mouse model." (PMID 32968061, 2020).
cancer (31 papers, 1999 to 2026). A tumor composed of atypical neoplastic, often pleomorphic cells that invade other tissues. "Collectively, this study proposes that ASGR1 holds promise as a precise biomarker for early risk stratification and prognostic assessment in HCC, with potential application in cancer interception." (PMID 40852369, 2025). "Contrarily, positive expression of ASGR in CECs was more frequent in LC (42.9%; 18/42) than in HCC without prior LC (22.2%; 2/9), suggesting that LC patients (independently on their cancer status) were more likely to have ASGR1 positive CECs." (PMID 36518850, 2022). "Furthermore, the percentage of ASGR1 expression in CECs decreased with Child Pugh-Turcotte stage suggesting it may be used as diagnostic and prognostic biomarker in earlier disease stages as an outstanding cancer interception tool." (PMID 36518850, 2022). "ASGR1 is also believed to be involved in the occurrence and progression of certain cancers." (PMID 40429734, 2025). "Additionally, IHC staining of the HC-04 cell line confirmed the presence of the receptor asialoglycoprotein receptor 1 (ASGPR1), an essential receptor for hepatocyte targeted drug delivery, which is associated with drug uptake in cancer cells." (PMID 36928885, 2023). "Targeting ASGR1 could represent an essential strategy for cancer treatment." (PMID 40429734, 2025). "Those 6 genes in the model (PDK4, MPP1, ASGR1, MS4A14, FCER1A and MX2), rarely reported in cancers, were found to be significantly related to the prognostic survival of KIRC patients." (PMID 34606472, 2021). "Presence of CECs without ASGR1 expression significantly correlated with cancer occurrence (p = 0.012)." (PMID 36518850, 2022). "Finally, overall survival was significantly greater for patients at earlier cancer stages (p = 0.018), but this difference was only maintained in the group with the presence of CECs (p = 0.021) whereas progression-free survival was influenced by the absence of ASGR1 expression." (PMID 36518850, 2022).
cardiovascular disease (11 papers, 2021 to 2026). "In humans, loss-of-function variants of ASGR1 are associated with a favorable metabolic profile and reduced incidence of cardiovascular diseases." (PMID 38281933, 2024). "Loss-of-function variants of Asialoglycoprotein receptor 1 (ASGR1) were associated with low cholesterol and a reduction in cardiovascular disease." (PMID 38667744, 2024). "Genetic variants in the asialoglycoprotein receptor 1 (ASGR1) are associated with a reduced risk of cardiovascular disease (CVD) in humans." (PMID 34762653, 2021). "Currently, a novel anti‐ASGR1 monoclonal antibody named AMG 529 has been developed for the treatment of cardiovascular diseases, but it remains in the clinical research stage." (PMID 39949133, 2025). "A population genetic study identified that the asialoglycoprotein receptor 1 (ASGR1) mutation carriers had substantially lower non–HDL-cholesterol (non–HDL-c) levels and reduced risks of cardiovascular diseases." (PMID 34622799, 2021). "Loss of asialoglycoprotein receptor 1 (ASGR1), the major subunit of ASGPR in humans, was found to correlate with lower levels of plasma apolipoprotein B-containing lipoproteins (B-lps) and a profound reduction in cardiovascular disease risk." (PMID 42264088, 2026). "Given its multiple roles in lipid regulation, ASGR1 may represent a novel therapeutic target for cardiovascular disease." (PMID 40852369, 2025). "This work strongly suggests that reduction of ASGR1 could reduce cardiovascular disease in the general human population." (PMID 34762653, 2021). "Anti-ASGR1 neutralizing antibodies in mice show synergistic effects on serum cholesterol relative to some currently used lipid modifiers (i.e. statins and ezetimibe), highlighting ASGR1 as a possible therapeutic target for lowering cholesterol and preventing cardiovascular diseases (CVD)." (PMID 37400795, 2023). "In conclusion, therapies targeting ASGR1 represent a novel treatment for lowering non‐HDL cholesterol levels and treating cardiovascular disease, particularly CAD." (PMID 38344397, 2024). "Recent genetic studies indicated that a rare loss-of-function variant in the ASGR1, resulted in a significant reduction in blood levels of “non-HDL” cholesterol, and a 34% reduction in cardiovascular diseases risk." (PMID 38281933, 2024). "The loss-of-function variants in the ASGR1 are associated with a significant reduction in cholesterol levels in non-HDL lipoproteins and a 34% reduction in a predicted cardiovascular disease (CVD) risk." (PMID 39616371, 2024).
infection (10 papers, 2016 to 2025). The state of being infected such as from the introduction of a foreign agent such as serum, vaccine, antigenic substance or organism. "Collectively, these findings indicate that ASGR1 is a candidate receptor for SARS-CoV-2 that promotes infection of hepatic parenchymal cells." (PMID 38355848, 2024). "Recently, it has been shown that KREMEN1 and ASGR1 can mediate entry into cells and that the expression of these two receptors and ACE2 correlates more with susceptibility to infection than either receptor alone." (PMID 38436242, 2024). "After inhibiting ASGR1 in primary hepatic parenchymal cells by siRNA, the infection efficiency of the live virus decreased significantly." (PMID 38355848, 2024). "Given the role of ASGR1 in modulating the recognition of desialylated glycoproteins, which is crucial during infection and inflammatory conditions, we investigated the effect of ASGR1 deficiency on the immunoinflammatory response observed during atherogenesis." (PMID 39616371, 2024). "However, after treatment with ASGR1 antibody or siRNA targeting ASGR1, the infection rate significantly dropped, suggesting that SARS-CoV-2 pseudovirus infects hepatic parenchymal cells mainly through an ASGR1-dependent mechanism." (PMID 38355848, 2024). "Compared with the control-siRNA and ACE2-knockdown group, ASGR1-knockdown could significantly reduce the infection of hepatocytes by SARS-CoV-2." (PMID 38355848, 2024). "Thus, in primary hepatocytes, ASGR1 is the main infection receptor of SARS-CoV-2." (PMID 38355848, 2024). "Considering that under physiological conditions, ASGR1 can promote the endocytosis of glycoproteins containing N-acetyl galactosamine residues by binding to N-acetyl galactosamine, we tried to further explore whether N-acetyl galactosamine blocks the infection of hepatocytes by SARS-CoV-2." (PMID 38355848, 2024). "Cellular molecules, including KREMEN1, ASGR1, and CD147 have been shown to mediate viral uptake, while infection enhancing molecules, such as the phosphatidylserine receptor, facilitate viral internalization in an ACE2-dependent manner." (PMID 35711449, 2022). "Taken together, we confirm that ASGR1 could bind to the RBD and NTD regions of Spike protein and the infection dependent on RBD." (PMID 38355848, 2024). "Intriguingly, compared to other host receptors of SARS-CoV-2, such as ACE2, ASGR1, KREMEN1, and TMEM106B exhibits broader and higher expression levels in both cell lines and tissues, implying that TMEM106B may facilitate the infection of ACE2-negative cells in diverse tissues." (PMID 41147188, 2025). "It was found that neither A779 nor UDCA could inhibit the infection of SARS-CoV-2 in THLE-2 or primary hepatocytes, but soluble ASGR1 protein could." (PMID 38355848, 2024).
heart disease (1 paper, 2016). "This has shed some light on a new path – the sialylation pathway – possibly leading to a novel therapy that neutralize ASGR1 for heart disease prevention and treatment." (PMID 29043262, 2016). "This has shed some light on a new path – the sialylation pathway – which could represent an initial step towards a novel therapy that neutralizes ASGR1 for heart disease prevention and treatment." (PMID 29043262, 2016).
liver (1 paper, 2024). "To further investigate the role of ASGR1 in chronic liver injury, we treated mice with CCl4 for 6 weeks to induce chronic liver injury." (PMID 38459023, 2024).
ASGR1 also shares sentences with these, for which no sentence is quoted: liver fibrosis (7 papers); metabolic disorders (3); viral hepatitis (3); alcoholic hepatitis (2); autoimmune hepatitis (2); breast carcinoma (2); cervical cancer (2); cholangiocarcinoma (2); dyslipidemia (2); Hepatitis (2); Hypertension (2); prostate carcinoma (2); Acute hepatic porphyria (1); adenovirus infection (1); alcohol abuse (1); Alzheimer disease (1); amyloidosis (1); autoimmune disease (1); bacterial infections (1); colon cancer (1); colorectal adenocarcinoma (1); heart failure (1); Hepatic steatosis (1); hepatitis B (1); hepatitis C (1); hyperlipidemia (1); immune dysfunction (1); leukemia (1); liver tumors (1); malaria (1).
A further 8 diseases each share a sentence with ASGR1 in 1 paper.